MAP2 (microtubule associated protein 2)
Diseases named in the same sentence as MAP2 in open-access papers (continued):
Sharing a sentence is not in itself a finding about the gene and the disease.
neuroblastoma (35 papers, 2011 to 2026). Neuroblastoma (NB) is the most common solid, extracranial childhood tumor. "We showed that overexpression of SVCT2 in the neuroblastoma Neuro2a cell line induces numerous microtubule-associated protein 2 (MAP2)-positive processes and filopodia." (PMID 34573045, 2021). "In neuroblastoma and glioblastoma cells, for instance, Oxtr agonists differentially regulate the genes encoding Nestin and Map2." (PMID 28231043, 2017). "Moreover, PRL increases both the expression and protein levels of Nestin and microtubule-associated protein 2 (MAP2) in neuroblastoma (SK-N-SH) cells." (PMID 27065946, 2016). "These spheroids are differentiated into mature neurons (MAP2-positive) and cholinergic neurons (ChAT-positive) from human neuroblastoma cells." (PMID 40711147, 2025). "Fate 2, corresponding to cluster cIVS, exhibited increasing expression of neuronal function markers NPY, MAP2, GAP43, and GATA2, which are associated with differentiating neuroblastomas." (PMID 40448172, 2025). "Researchers used immunohistochemical analyses of tissue microarrays to evaluate the utility of a commercially available antibody against MAP2 in detecting primary and metastatic neuroblastomas." (PMID 36230740, 2022). "At the same time, MAP2 is expressed explicitly in neuroendocrine carcinoma and relevant tumor cell lines, such as small cell lung cancer and neuroblastoma." (PMID 34660263, 2021). "Cells were incubated with Ang II (600 nM) for 24 h, and MAP2 and NF-H levels were measured by flow cytometry to monitor neuroblastoma differentiation." (PMID 34285710, 2021). "In fact, MAP2 has been shown to be specifically expressed in neuroendocrine carcinoma and relevant tumor cell lines, such as small cell lung cancer and neuroblastoma." (PMID 34660263, 2021). "Another in vitro study demonstrated the neuroprotective effect of curcumin, which up-regulates MAP2 expression in human neuroblastoma cells treated with Aβ oligomers." (PMID 32046281, 2020). "Gene expression of markers distinctive for differentiated neurons, such as microtubule-associated protein 2 (MAP2) and synaptophysin (SYP), indeed confirmed that MRx0029 induced a differentiated phenotype in neuroblastoma cells." (PMID 31619962, 2019). "A retinoic acid-differentiated neuroblastoma line (SH-SY5Y) that expresses both tau and the short isoform of MAP2, called MAP2c, was also cross-linked and immunoprecipitated." (PMID 28683104, 2017). "Next, we examined the role of H89 pretreatment on the expression of brain-derived neurotrophic factor (BDNF), PSD95, MAP2, and the apoptosis regulators Bcl2 and cleaved caspase-3 in cultured neuroblastoma cells exposed to hypoxia and reperfusion injury." (PMID 26448879, 2015). "Exposure of SK-N-SH neuroblastoma cell line to cytotoxic PrP106-126 peptide significantly down-regulated the cellular MAP2 level and remarkably disrupted the microtubule structure, but did not alter the level of tubulin." (PMID 22272295, 2012). "Flow cytometric analysis confirmed differences in the expression of MAP2, β-catenin, and PDGFRβ while all neuroblastoma cells were nestin positive." (PMID 22891161, 2012). "Treatment of Aβ1–42 on C57BL/6J mouse primary cerebral neurons and human neuroblastoma cells induce a reduction of MAP2." (PMID 22272295, 2012). "Notably, a study has reported that PKC-δ is activated during retinoic acid-induced neuroblastoma cell differentiation and regulates MAP2 expression." (PMID 40448172, 2025). "These suggest that Aβ monomers may promote the differentiation of neuroblastoma SH-SY5Y through activating MAP2 and Ezrin." (PMID 39125907, 2024). "Indeed, the addition of BDNF promotes molecular polarization in differentiating neuroblastoma cells leading to definitive neurons, which show an enrichment of MAP2 in the dendrite and tau in axons." (PMID 37627228, 2023).
neuroblastoma (continued). "MAP2 proteins have also been shown to be expressed in neuronally differentiated neurons A study seeking to establish the neural features of peripheral neuroblastic tumors analyzed samples of 12 neuroblastomas, 2 ganglioneuroblastomas, and 4 ganglioneuromas." (PMID 36230740, 2022). "Thus, the authors concluded that MAP2 is both a sensitive and specific marker to detect neuroblastoma and can differentiate neuroblastoma from other tumors with similar morphological features." (PMID 36230740, 2022). "In addition, we analyzed if the generation of neuroblastoma MAP2 expression and ROS levels were mediated through the activation of NADPH oxidase." (PMID 34285710, 2021). "Whether NGFR upregulation is instrumental and causal for the enhanced expression of NTRK2, NEFL, TUBB3, and MAP2 that we observe in the L-AN-5 neuroblastoma system, remains to be investigated." (PMID 33174841, 2020). "The biochemical differentiation profile of neuroblastoma cells overexpressing TMODs showed a significant increase of MAP2 and GAP43, mimicking then the “neuronal differentiation” obtained by retinoic acid, and an overall decrease of TH, DBH and CgA mRNA expression levels." (PMID 29930753, 2018). "Moreover, the reduction of MAP2 isoforms has been reproduced in a cultured neuroblastoma cell line exposed to the cytotoxic peptide PrP106–126 in this study." (PMID 22272295, 2012). "These phenomena could be reproduced in a human neuroblastoma cell line SK-N-SH exposed to the synthetic peptide PrP106–126, revealing the decrease of MAP2 and disruption of microtubule structures." (PMID 22272295, 2012). "Another study assessed whether MAP2 expression could be used in the diagnosis of neuroblastoma." (PMID 36230740, 2022). "When full-length MAPs fused with EGFP were expressed in human neuroblastoma (SH-SY5Y) cells, the microtubules in apical regions of protrusions expressing tau were straighter than in cells expressing MAP2 and MAP4." (PMID 37258650, 2023). "Although we found that ROS and MAP2 levels were increased simultaneously by Ang II through the activation of NADPH oxidase, the mechanism employed by ROS during neuroblastoma differentiation needs more investigation." (PMID 34285710, 2021). "Here, we also report an increase in TUBB3, MAP2, TH and DAT levels during neuroblastoma SH-SY5Y rho0 cell differentiation." (PMID 31717322, 2019). "Analysis of genes that are increased with retinoic acid induced differentiation of neuroblastoma cells (NGRF, NF68, NTRK1, SYP, MAP2, NEFM, DKK2) showed that all were elevated after 72 hours Wnt3a/Rspo2 treatment." (PMID 29505958, 2018). "In line with previously published analyses of HOXC9 in neuroblastoma cells, we found a significant up-regulation of genes involved in neuronal differentiation pathways such as DNER, NEFL, DBH, TH, RET, MAP2 and NPY." (PMID 25406647, 2014). "Each of these was supported by (i) the upregulation of KRT18, KRT19, E-cadherin, and downregulation of vimentin in breast carcinoma; (ii) increased levels of GFAP, MAP2, and PSD-95 in astrocytoma; and (iii) increased NeuN, GAP-43, and NF200 levels in neuroblastoma." (PMID 39859209, 2025). "We investigated the effects of TIR on markers of neuronal growth (CREB and BDNF), apoptosis (BAX/Bcl2 ratio) differentiation (pAkt, MAP2, GAP43, and AGBL4), and insulin resistance (GLUT1, GLUT4, GLUT3 and SORBS1) in a neuroblastoma cell line (SHSY5Y) exposed to normal and high glucose concentration." (PMID 38287296, 2024). "To determine whether the loss of TREX1 affects neuronal development, we knocked down the TREX1 gene in SH-SY5Y neuroblastoma cells and examined neuronal differentiation by immunocytochemical analysis of neuron-specific markers, such as TUBB3, MAP2, and NF-L." (PMID 34997539, 2022). "Our data revealed a significant increase in MAP2 expression levels when neuroblastoma cells were incubated with Ang II for 24 h; however, no significant changes were observed in NF-H levels when compared to untreated cells." (PMID 34285710, 2021).
neuroblastoma (continued). "A reduced expression level of Oct4, SOX2 and NESTIN was found, whereas TrkA, TH, MAP2 and TUJ1 was increased in USP3-silenced cells, suggesting that USP3 downregulation might impair self-renewal capacity in neuroblastoma." (PMID 37170124, 2023).
ischemia (32 papers, 2008 to 2025). A hypoperfusion of the BLOOD through an organ or tissue caused by a PATHOLOGIC CONSTRICTION or obstruction of its BLOOD VESSELS, or an absence of BLOOD CIRCULATION. "Using immunofluorescence microscopy, the loss of MAP2-related immunoreactivity allows a clear-cut detection of the ischemia-affected regions." (PMID 37342767, 2023). "Of note, ischemia-associated alterations are comprehensively indicated by changes of NF-L- and MAP2-related immunofluorescence intensity throughout the applied models in mice." (PMID 33931805, 2021). "In the setting of ischemic stroke, the neurofilament subunit NF-L and the microtubule-associated protein MAP2 have proven to be exceptionally ischemia-sensitive elements of the neuronal cytoskeleton." (PMID 33931805, 2021). "Of note, ischemia-related loss of MAP2 labeling co-localized with a clear-cut enhancement of the NF-L-related immunoreactivity." (PMID 29967576, 2018). "Microtubule-associated protein-2 (MAP-2) is depleted in the early hours after an in vivo ischemia insult in a rat hippocampal slice." (PMID 30524653, 2018). "Conversely, the addition of LPA attenuated TMP’s inhibitory effect on the RhoA/ROCK pathway, consistent with other studies, and MAP2, a dendritic plasticity-related protein sensitive to ischemia, were both upregulated by TMP treatment." (PMID 40495884, 2025). "Toward ischemia, filaments detected by MAP2 and MFAP5 appeared fragmented, and the immunosignal of β3-tubulin was found markedly diffused." (PMID 40548074, 2025). "Comparable regional associations of MAP2, β3-tubulin, and MFAP5 were observed in the border zone on the ischemia-affected hemisphere." (PMID 40548074, 2025). "Two days after the onset of ischemia, MAP2 immunoreactivity was markedly decreased in the left cerebral cortex, whereas TUJ1 immunoreactivity remained positive." (PMID 37636590, 2023). "Regarding MFAP5, a decreased immunosignal was observed in the ischemia-affected neocortex, accompanied by a decreased MAP2 signal and a slightly increased appearance of NF-L (E’)." (PMID 37569268, 2023). "Compared with contralateral control regions, the intensity of MAP2-related immunofluorescence decreased 24 h after ischemia induction." (PMID 36151103, 2022). "Contrary to the reduced immunofluorescence intensity of MAP2 in infarcted regions, the NF-L-related immunofluorescence intensity is apparently increased in ischemia-affected areas." (PMID 33931805, 2021). "In general, neurofilaments and MAP2 have been recognized as elements of the neuronal cytoskeleton, which are exceptionally prone to ischemia-mediated damage." (PMID 33931805, 2021). "While the ischemic region is regularly characterized by a decreased MAP2-related immunofluorescence intensity, the NF-L-related immunofluorescence intensity appears to be increased 24 and 72 h after ischemia induction." (PMID 33931805, 2021). "Taking these aspects into consideration and given that the serum levels of MAP2 exhibited a more pronounced increase compared to NF-L, MAP2 is likely to represent a more sensitive biomarker for early ischemia-induced neuronal damage." (PMID 33931805, 2021). "The ischemia-induced reduction of MAP2 and NF-L full-length protein is further confirmed at the protein level, at the ultrastructural level, and by a decreased elastic strength of the ischemia-affected tissue." (PMID 33931805, 2021). "Here, we found that ischemia reduced the infarct area and the MAP2 level of expression, this effect represents an alteration in the microtubule structure of the cytoskeleton and signifies a reduction in the number of surviving neurons." (PMID 32962200, 2020). "On the contrary, the levels of neuron-specific Microtubule-Associated Protein 2 (MAP-2) and tight junction ZO-1 protein were downregulated by ischemia." (PMID 32492962, 2020). "As an ischemia-sensitive marker, MAP2 immunoreactivity is decreased in ischemic areas of the ischemic core and the surrounding penumbral areas." (PMID 30744693, 2019).
ischemia (continued). "Another potential mediator is calpain, which degrades the neuronal cytoskeleton, preferentially targeting Map2, very early after ischemia." (PMID 28729941, 2017). "To assess neuronal survival under these conditions, we quantified the neurons subjected to in vitro ischemia using MAP2-ir staining." (PMID 24887017, 2014). "However, the local arrangement of MFAP5 and its change due to ischemia was comparable to that of NF-L and MAP2." (PMID 40548074, 2025). "MAP2 intensity is commonly used in ischemia studies but may also be an early marker of neuronal damage." (PMID 39941015, 2025). "Along with an altered immunosignal of the cytoskeletal elements MAP2 and NF-L in the ischemia-affected neocortex, the present study revealed a gradually decreasing signal of tricellulin, MFAP5 and α-catenin toward the ischemic region of the neocortex, and also in the ischemic subcortex." (PMID 37569268, 2023). "Compared with the contralateral, non-affected hemisphere, a gradual decrease in the tricellulin signal was observed along the neocortex toward the ischemia-affected area, accompanied by decreasing signals of MAP2 and NF-L, which was also found in the subcortex." (PMID 37569268, 2023). "However, while ischemia-affected areas are characterized by a reduction of MAP2-related fluorescence intensity, an opposite effect as indicated by an increased intensity is observed for CNP, MBP, collagen IV, and laminin." (PMID 37342767, 2023). "Accompanied by the decreasing immunosignal of MFAP5 along the ischemia-affected neocortex, signals of MAP2 and NF-L decreased significantly (p-values ranging from 0.014 to 0.027), even though in this subset of analyses NF-L was found to decrease to a lesser degree." (PMID 37569268, 2023). "This alteration was accompanied by a notably decreasing MAP2 signal in the border zone of ischemia." (PMID 37569268, 2023). "Interestingly, this parallels findings from brain injury models, such as ischemia and traumatic spinal cord injury, which also describe calpain-mediated MAP2 degradation." (PMID 36187353, 2022). "As MAP2 was further shown to be reduced earlier due to ischemia than NF-L, these regional differences may reflect the heterogeneous distribution of NF-L or also regional differences of the ischemic affection within the ischemic lesion." (PMID 33931805, 2021). "MAP2, a cytoskeletal phosphoprotein, is reported to degrade after ischemia and other injuries." (PMID 28352215, 2017). "Concomitantly observed alterations in cellular NVU constituents thereby support the assumption that a critical affection of cell-stabilizing elements, such as MAP2 and NF-L, represents a key mechanism for cellular degeneration due to ischemia and might be considered a neuroprotective target." (PMID 37569268, 2023). "While the MAP2 signal began to decrease in the medial part of the border zone, NF-L markedly decreased in the middle or lateral part of the border zone, which is a finding that is comparable with a previous investigation of these markers in the ischemia-affected brains of mice." (PMID 37569268, 2023). "These alterations were accompanied by a partially increased NF-L signal within the ischemic border zone and a markedly decreased MAP2 signal toward the ischemic area, representing cytoskeletal and thus cell-stabilizing elements that have already shown high vulnerability in the setting of ischemia." (PMID 37569268, 2023). "At day 7 and day 14 after I/R, most of the MAP2+ dendrites disappeared and the numbers of MAP2+ cells were dramatically reduced in the penumbra of the vehicle group, which indicated the most severe injury of the neurons induced by ischemia occurred in this duration." (PMID 29765502, 2018). "Noteworthy, 4 h after ischemia induction, BBB breakdown is found to exceed the areas of ischemia-related MAP2 downregulation in cortical and striatal areas." (PMID 30744693, 2019).
ischemia (continued). "Double-immunofluorescent labelling of brain slices from rats 24 h post-ischemia confirmed that these STI-1-expressing cells included Neu-N+ neurons, GFAP+ glia, MAP-2+ neurons and vWF+ vascular endothelial cells." (PMID 23836498, 2013). "Thereby, MFAP5 displayed similarities with MAP2 and NF-L concerning morphological characteristics in non-affected brain regions and exhibited comparable changes due to ischemia." (PMID 40548074, 2025). "In addition to the loss of NeuN immunoreactivity, we also found significant losses of MAP2 immunoreactivity in the pyramidal layers of CA1 and part of CA3, suggesting degeneration of neuronal dendrites induced by ischemia." (PMID 33244072, 2020). "The expression of MAP2 was higher in the MCAO+MIF group than in the MCAO+veh group (* p < 0.0001), indicating that neuronal viability may be increased if the MIF were administered even after experiencing ischemia." (PMID 35805977, 2022). "Interestingly, neither the MAP2- nor the NF-L-related immunofluorescence intensity differed significantly between transient and permanent ischemia (4h-t vs. 4h-p; 24h-t vs. 24h-p; 72h-t vs. 72h-p)." (PMID 33931805, 2021). "Nevertheless, a study using a BCCAO model reported a similar MAP-2 pattern, with reductions in MAP-2 in the CA1 subfield, but not in the CA2 and CA3 subfields, 4 days post-ischemia." (PMID 40869376, 2025). "Considering the short time window of our observation (max 3 hours after the induction of ischemia), we cannot exclude that NCs could migrate in a later phase from the MAP-2 positive penumbra regions towards the MAP-2 negative ischemic zone." (PMID 18648648, 2008).